LMNA (lamin A/C)
Diseases named in the same sentence as LMNA in open-access papers (continued):
Sharing a sentence is not in itself a finding about the gene and the disease.
laminopathies (continued). "Mutations in the LMNA gene, encoding A-type lamins, cause a number of different tissue specific laminopathies, including DCM." (PMID 28398466, 2017). "In conclusion, our study highlights the multiple deleterious impacts of the LMNA p.R388P mutation, responsible for a complex and severe multisystemic laminopathy phenotype, on the organisation of the nuclear compartment in myoblasts." (PMID 28125586, 2017). "Mutations in LMNA, encoding nuclear intermediate filament proteins lamins A and C, cause multiple diseases (‘laminopathies’) including muscular dystrophy, dilated cardiomyopathy, familial partial lipodystrophy (FPLD2), insulin resistance syndrome and progeria." (PMID 28663758, 2017). "Accordingly, the extinction of lamin A/C by siRNA or the expression of laminopathy-associated mutant lamins A/C induces abnormal nuclear shapes." (PMID 28125586, 2017). "Patients bearing such LMNA gene mutations show phenotypes corresponding to muscle-related laminopathies." (PMID 27534416, 2017). "Mutations in LMNA gene, encoding Lamin A/C, cause a diverse array of phenotypes, collectively referred to as laminopathies." (PMID 29047356, 2017). "The best-known laminopathy phenotypes are based on mutations in the LMNA gene (autosomal), which encodes for lamins A and C, and the EMD gene (X-linked), which encodes for emerin." (PMID 27534416, 2017). "Mutations in the LMNA gene cause a diverse array of phenotypes, which are collectively referred to as laminopathies." (PMID 29047356, 2017). "Mutations in LMNA have been shown to cause a wide range of human diseases, collectively referred to as “laminopathies”." (PMID 27649756, 2016). "A-type lamins have been widely discussed since the discovery that LMNA mutations or defective posttranslational processing of pre–lamin A causes the majority of human diseases (termed laminopathies) that are accompanied with shortened telomere lengths." (PMID 27347007, 2016). "Apart from pharmacological treatment of LMNA mutation-related disease, there were new breakthroughs in gene editing technologies for correction of laminopathy-associated LMNA mutations in patient-specific iPSCs." (PMID 27649756, 2016). "HGPS is classified as a laminopathy since it is caused by mutations in the LMNA gene, which encodes the lamin A and C proteins by alternative splicing." (PMID 26053873, 2015). "Dysregulation of genes involved in organizing and maintaining nuclear structures, such as SYNE1, SYNE2, TREM43, EMD and LMNA is frequently associated with diverse diseases termed laminopathies, which often affect the muscle tissue." (PMID 25906157, 2015). "For example, laminopathy-based premature aging syndromes (collectively known as laminopathies) originate from mutations in the LMNA gene or ZMPSTE24 gene." (PMID 25907989, 2015). "Among all the nuclear lamina components, LMNA is the first and most studied gene associated with laminopathies." (PMID 25906157, 2015). "Laminopathies are genetic diseases caused by mutations in the gene LMNA, which encodes nuclear lamins A/C, or in genes encoding proteins that interact with lamins A/C." (PMID 25645366, 2015). "Most laminopathies arise due to a single point mutation in one of the LMNA alleles and are thus autosomal dominant." (PMID 23451281, 2013). "This is in marked contrast to LMNA, mutation of which results in several clinically distinct diseases, termed laminopathies." (PMID 23733478, 2013). "Mutations in LMNA have been identified as the cause of at least 12 different inherited disorders, known as laminopathies, which have significant phenotypic overlap." (PMID 23497705, 2013). "Mutations in human LMNA have been linked to a spectrum of degenerative genetic diseases that are termed as laminopathies." (PMID 23451281, 2013). "A group of these laminopathies have been classified as progeroid syndromes that can be caused by mutations in LMNA or ZMPSTE24." (PMID 23804595, 2013).
laminopathies (continued). "In the present study, we identified a fatal RD-like disease as a distinct primary progeroid laminopathy linked to the homozygous pathogenic LMNA mutation c.1303C>T (p.R435C)." (PMID 23804595, 2013). "Patient N showed two missense changes in LMNA including the p.Arg644Cys change, previously linked to various laminopathies." (PMID 22526018, 2012). "Mutations in LMNA encoding lamins A and C are associated with at least 10 different degenerative disorders affecting diverse tissues, collectively called laminopathies." (PMID 22709970, 2012). "Within the LMNA gene alone, over 400 different point mutations have been identified, many of which are underlying causes of laminopathies, including restrictive dermopathy (MIM 275210) and Hutchinson–Gilford progeria syndrome (HGPS; MIM 176670)." (PMID 23090008, 2012). "In line with the well-established role of A-type lamins in maintaining higher order chromatin organization, laminopathy-associated point mutations in the lamin A/C gene (LMNA) often deregulate chromatin structure and organization." (PMID 22610065, 2012). "In a mouse model of another laminopathy, autosomal Emery-Dreifuss muscular dysfunction due to a missense H222P LMNA mutationalso manifests with DCM and atrioventricular conduction abnormality." (PMID 23362510, 2012). "Mutations in the LMNA gene are responsible for a broad range of phenotypically distinct disorders called laminopathies." (PMID 21980471, 2011). "Today, there are at least a dozen different genetic disorders caused by mutations within the LMNA gene, and collectively, they are named laminopathies." (PMID 21980471, 2011). "Our method should be useful for further studies of human samples with mutations in the LMNA gene and to increase the understanding of the link between genotype and phenotype in laminopathies." (PMID 21980471, 2011). "Mutations in LMNA are associated with a broad range of laminopathies, congenital diseases affecting tissue regeneration and homeostasis." (PMID 21151901, 2010). "Mutations in the LMNA gene, which encodes all A-type lamins, result in a variety of human diseases termed laminopathies." (PMID 20405040, 2010). "The mutations in the LMNA gene has been shown to cause at least nine different autosomal recessive and dominant genetic diseases, collectively called laminopathies." (PMID 21151901, 2010). "Mutations in LMNA cause phenotypically heterogenous, mostly autosomal-dominant inherited diseases, termed laminopathies." (PMID 20498701, 2010). "Mutations in LMNA have been found in 11 clinically distinct tissue-specific degenerative diseases collectively termed "laminopathies", including muscular dystrophy, cardiomyopathy, lipodystrophy, and progeria." (PMID 19849840, 2009). "Mutations in the mammalian lamin A/C gene cause a range of diseases, collectively called laminopathies, that include muscular dystrophies and premature aging disorders." (PMID 17565385, 2007). "As a proof of concept of this idea, we were able to use the microgrooves to demonstrate significant differences in nuclear shapes between healthy myoblasts and myoblasts carrying three different mutations in the LMNA gene that cause severe muscular dystrophies (laminopathies)." (PMID 39873289, 2025). "This article underlines the well-known phenotypic heterogeneity of laminopathies and supports the hypothesis of a disease linked to LMNA variants." (PMID 40783787, 2025). "Indeed, there are data on literature that the LMNA mutations–induced defects in the positioning of synaptic nuclei at the NMJ in muscle fibers contribute to the laminopathy with skeletal muscle phenotype development and progression." (PMID 39948343, 2025). "In the case of LMNA mutations present in laminopathies, the abnormal nuclear deformations observed in this study likely reflect a lack of this structural and mechanical plasticity, resulting in an inability of nuclei to cope with the physical constraints imposed by the extracellular environment." (PMID 39873289, 2025).
laminopathies (continued). "LMNA mutation is responsible for laminopathies, including LMNA -cardiomyopathy." (PMID 38476290, 2024). "We used muscle cells as a model system, as both lamins and LAP2α were previously shown to affect skeletal muscle differentiation in vitro and in vivo, and striated muscle laminopathies are among the most frequent diseases associated with mutations in LMNA in humans." (PMID 39228367, 2024). "Furthermore, these findings have natural implications for laminopathies – diseases that are characterized by mutations in LMNA." (PMID 39140137, 2024). "Separately, we tested possible effects of mutations in LMNA, the gene controlling expression of lamin A. We considered a combination of two alterations to the model due to this mutation, aiming to mimic states relevant to laminopathies." (PMID 39140137, 2024). "Besides, it is already known that the laminopathy-associated nuclear dysmorphia results from LMNA gene mutations, which lead to loss of the nuclear lamina integrity." (PMID 39542246, 2024). "The mutations in LMNA could cause various diseases which called laminopathies, such as LMNA-related dilated cardiomyopathy (LMNA-DCM), Emery-Dreifuss muscular dystrophy (EDMD), lipodystrophy, skeletal dysplasia, and Hutchinson-Gilford progeria syndrome (HGPS)." (PMID 37784143, 2023). "Mutations in the LMNA gene cause laminopathies, disorders with diverse phenotypic manifestations." (PMID 37025686, 2023). "We created Caenorhabditis elegans models for striated muscle laminopathies by introducing pathogenic human LMNA variants and variants of unknown significance at conserved residues within the lmn-1 gene." (PMID 37624850, 2023). "LMNA mutations can lead to a group of progeroid laminopathies, including cardiovascular disorders." (PMID 37461109, 2023). "Therefore, it is unsurprising that pathogenic or haploinsufficient LMNA mutations, which are linked to laminopathies, have adverse effects on the epigenome." (PMID 37052760, 2023). "Mutations in LMNA lead to a wide range of diverse diseases called laminopathies." (PMID 37884611, 2023). "Pathogenic mutations and haploinsufficiency in genes encoding nuclear lamina proteins, particularly LMNA, result in a collection of syndromes referred to as laminopathies, which includes myopathies, lipodystrophies, neuropathies, and segmental progeroid syndromes." (PMID 37052760, 2023). "Indeed, we observed a fundamental link between the laminopathy‐associated E262K mutation of LMNA and the induction of nuclear proteotoxicity." (PMID 36225129, 2022). "In addition, mutations in LMNA induce common laminopathies characterized by multiple rare clinical symptoms, including muscular dystrophy, lipodystrophy, diabetes, dermopathy, neuropathy, leukodystrophy, and progeria." (PMID 36552752, 2022). "Several of the laminopathy‐associated sequence variations in LMNA are known to induce alternative splicing by introducing cryptic splice sites in LMNA pre‐mRNA, resulting in the formation of different isoforms of LMNA protein." (PMID 36225129, 2022). "The lack of SUMOylation of aggregated LMNA mutant has been reported previously, and our finding of the loss of SUMOylated LMNAE262K in laminopathy‐associated progeroid condition supports the idea that aggregated nuclear LMNA restricts its SUMOylation by one or more mechanisms." (PMID 36225129, 2022). "Based on the mutation in LMNA, laminopathies are classified into typical and atypical forms." (PMID 36225129, 2022). "Laminopathies are a spectrum of diseases caused by LMNA mutations." (PMID 36552752, 2022). "Laminopathies define a heterogeneous group of diseases linked to mutations in the LMNA gene." (PMID 36104080, 2022). "FPLD2 belongs to a family of laminopathies, characterized by mutations in the LMNA gene." (PMID 35920656, 2022).
laminopathies (continued). "Mutations in LMNA have been linked to physiological aging, as well as degenerative disorders, broadly termed laminopathies, including muscular dystrophy, neuropathies, lipodystrophies, and the premature aging syndrome Hutchinson-Gilford Progeria syndrome (HGPS)." (PMID 36099415, 2022). "Mutations in the LMNA gene cause severe genetic diseases called laminopathies." (PMID 35935653, 2022). "While pathogenic LMNA variations underpinning laminopathies have been clinically defined, it remains unclear how these mutations alter lamin A/C function and how the subsequent dysregulation impacts phenotypic outcomes." (PMID 36503349, 2022). "Together with the involvement of S100A6 in LMNA-related muscular dystrophy from our study, altered calcium cycling might be a common disturbance due to LMNA mutations, although the involved calcium regulators may differ in different subtypes of laminopathy." (PMID 36555163, 2022). "Dunnigan syndrome, or Familial Partial Lipodystrophy type 2 (FPLD2), is a rare autosomal dominant genetic disorder belonging to the large group of laminopathies, diseases related to pathogenic variants of the LMNA gene that encodes lamin A/C, proteins in the envelope of the cell nucleus." (PMID 35440056, 2022). "Such is the case of CMT2-B1, a laminopathy caused by a point mutation in the Lamin A (LMNA) gene." (PMID 35327648, 2022). "Laminopathies are a group of rare disorders due to mutation in LMNA gene." (PMID 34768351, 2021). "Furthermore, it was previously shown that methylation levels varied at the promoter of laminopathy-related genes in cells with two distinct LMNA mutations." (PMID 34246298, 2021). "Several laminopathies have been reported based on their LMNA mutation." (PMID 34944031, 2021). "These rare diseases are termed laminopathies and are mostly caused by LMNA mutations." (PMID 34638534, 2021). "In addition to the structural roles of A-type lamins, Lamin A/C has been shown to play a role in the regulation of gene expression and cell cycle progression, and alterations in the LMNA gene is cause of human diseases called laminopathies." (PMID 33980953, 2021). "This, in turn, may explain the phenotypic heterogeneity observed in laminopathy patients where over 400 mutations in the ubiquitously expressed LMNA gene have been described to date." (PMID 33802236, 2021). "In this review, we describe the pathophysiological mechanisms implicated in laminopathies, i.e., the diseases due to LMNA gene mutations, with a focus on SML and premature ageing syndromes, and associated preclinical therapies that have been developed over the years." (PMID 34768351, 2021). "Mutations in the LMNA gene cause diseases called laminopathies." (PMID 34681887, 2021). "Given that nucleoporins interact with specific chromatin domains, nuclear pore clustering could regulate local chromatin organization and contribute to the disease phenotypes caused by human lamin A/C laminopathies." (PMID 34806753, 2021). "Although the mechanisms by which LMNA mutations cause laminopathies remain unknown, a number of molecular changes have been reported in cells or tissues derived from laminopathy patients or in animal or cellular models of laminopathies." (PMID 33030403, 2020). "Although it remains unclear exactly how mutant LMNA causes laminopathies, it is believed that both gain of pre–lamin A’s toxic functions and loss of mature lamin A/C’s physiological functions contribute to the disease pathology." (PMID 32479501, 2020). "On the other hand, because LMNA exons 3 and 5 are in frame, exon 4 skipping might be considered as a therapeutic strategy for all those laminopathies associated with LMNA exon 4 mutations." (PMID 32455813, 2020).
laminopathies (continued). "LMNA mutations predominantly affect mesoderm-derived cell lineages in diseases collectively termed as laminopathies that include dilated cardiomyopathy with conduction defects, different forms of muscular dystrophies, and premature aging syndromes as Hutchinson-Gilford Progeria Syndrome." (PMID 32698886, 2020). "Why do family members with the same LMNA mutations develop different laminopathies?" (PMID 32796718, 2020). "Laminopathies are a heterogeneous group of genetic disorders caused by mutations in LMNA, which encodes nuclear A-type lamins: lamins A and C. Generated by alternative splicing, lamins A and C are identical for most of their sequence but differ from their C-terminal domains." (PMID 33036437, 2020). "Laminopathies, due to mutations in LMNA, encoding A type-lamins, can lead to premature ageing but also to lipodystophic syndromes, showing that these diseases may have related physiopathological mechanisms." (PMID 31752481, 2020). "Laminopathies are causally associated with mutations on the Lamin A/C gene (LMNA)." (PMID 32455813, 2020). "The laminopathy mutations in LMNA cause nonsynonymous substitutions in the vast majority of cases." (PMID 33030403, 2020). "Laminopathies are a group of genetic disorders caused by mutations at the LMNA locus." (PMID 32954377, 2020). "Lamin A/C, a nuclear lamina protein, is implicated in the pathogenesis of various laminopathies." (PMID 32479501, 2020). "Diseases involving lamin proteins are called laminopathies and can be primary or secondary Primary laminopathies are caused by mutation of the LMNA gene, and secondary laminopathies are caused by Zmpste24 defects, which prevents prelamin A from successfully being converted to lamin A." (PMID 33316938, 2020). "Although these observations demonstrate the important function of lamin A/C to prevent laminopathies, it remains unclear exactly how the loss of lamin A/C affects multiple tissues and promotes various types of laminopathies." (PMID 32479501, 2020). "Investigation of the effects of LMNA mutations on the expression of human TEs could be useful to understand a possible role of TEs in laminopathies and could help to find an explanation to the high phenotype variability observed in muscular laminopathies." (PMID 32151001, 2020). "Disruption or mutation of the LMNA gene is associated with a disease called laminopathy." (PMID 30901896, 2019). "LMNA mutations induce a complex set of pathological conditions collectively termed laminopathies." (PMID 30862117, 2019). "The potential molecular mechanism underlying this association could involve cell proliferation/differentiation process in progenitor cells during development similar to that reported for LMNA mutations responsible for different laminopathy conditions." (PMID 29963074, 2018). "Mutations in LMNA gene cause a wide and heterogeneous group of diseases belonging to the category of laminopathies, which may affect skeletal and cardiac muscle, bone, adipose tissue and peripheral nerves and may be associated with accelerated ageing." (PMID 29854317, 2018). "Mutations in the human LMNA gene cause a collection of diseases known as laminopathies." (PMID 29575479, 2018). "Together, mutations in LMNA cause tissue-specific signaling and transcriptional abnormalities of progenitor cells and could explain inefficient terminal differentiation seen in laminopathies." (PMID 29750601, 2018). "Strikingly, the different LMNA mutations, located all along the gene, give rise to very diverse clinical phenotypes of laminopathies, comprising not only lipodystrophic syndromes but also dystrophic myopathies, neuropathies, premature ageing syndromes and rare overlapping syndromes." (PMID 29578370, 2018). "Mutations in LMNA cause at least 16 rare disorders, collectively known as laminopathies." (PMID 30405424, 2018).